KRAS (KRas proto-oncogene, GTPase)
Diseases named in the same sentence as KRAS in open-access papers (continued):
Sharing a sentence is not in itself a finding about the gene and the disease.
tumor (continued). "Furthermore, when organoids with the KRAS mutation were treated with some combination therapies that are currently being tested in clinical trials, the tumors stopped growing but the tumor cells failed to die." (PMID 27845624, 2016). "However, despite improved survival for a subset of patients, no benefit is seen for those with KRAS/NRAS mutated tumours." (PMID 27340376, 2016). "Genomic analysis revealed neither an ALK gene rearrangement nor EGFR, BRAF or HER2 gene mutations, but an activating point mutation of the KRAS gene (p.G12C, exon 2) and therefore this tumor could be considered a non-responder case to EGFR-TKI therapy." (PMID 27548442, 2016). "When we compared the gene expression profile of each tumor sample against a published KRas dependent gene signature, we found 94 % of our samples (112/118) to be KRas-dependent, which is in agreement with the fact that more than 90 % of PDAC have a KRAS driver mutation." (PMID 27520560, 2016). "Moreover, they indicated rare coexistence of the KRAS gene mutations with deletion in EGFR gene that was observed only in primary tumor but not in corresponding metastatic sample." (PMID 25902737, 2016). "Various laboratory-based or commercial KRAS mutation assays are used in routine practice and the majority of those have been optimized to be compatible with DNA extracted from formalin-fixed paraffin-embedded (FFPE) samples, which represent the most common form of tumor tissue specimens." (PMID 27685259, 2016). "Therefore it remains unclear whether the addition of irinotecan will provide additive benefit in patients selected for KRAS WT tumours." (PMID 27246726, 2016). "Thus, patients whose tumours harbour RAS mutations beyond KRAS exon 2 are unlikely to benefit from addition of panitumumab to FOLFIRI." (PMID 27764839, 2016). "Of the 31 primary tumor samples, one KRAS mutation was found in a non-responding patient." (PMID 26980732, 2016). "Tumors harboring oncogenic KRAS mutations, regardless of tumor site, have poor clinical outcomes." (PMID 26918447, 2016). "Furthermore, combination treatments may decrease the potency of low-abundant RAS mutant subclones to initiate tumor-relapse during therapy against a predominantly KRAS WT tumor." (PMID 27845624, 2016). "Plasma thymidine was significantly lower in SCID mice with AsPC-1 (p < 0.0001) or MiaPaCa-2 tumours (p = 0.0016) than in non-tumour bearing mice, but higher in mice with KPC tumours than in the PC mice, which lack the KRAS mutation and do not develop spontaneous tumours (p = 0.006)." (PMID 27515446, 2016). "Furthermore, the in vitro results showed that the repression of KRAS by miR-16 suppressed the proliferation and invasion and induced the apoptosis of CRC cells, and the in vivo results revealed that miR-16 exerted a tumor-suppressive effect by negatively regulating KRAS in xenograft mice." (PMID 27857191, 2016). "Moreover, activating mutations of KRAS as they occur in colon cancer downregulate STAT2 expression, which might contribute to the reduced sensitivity of tumor cells to interferons." (PMID 26938566, 2016). "This explains why the pyrogram from the whole tumor could not be interpreted as any specific KRAS mutation." (PMID 27597976, 2016). "Thus, targeting inhibition of MAPK-ERK signal pathways in cells that harboring KRAS, NRAS or BRAF mutation could suppress tumor growth." (PMID 26567773, 2015).
tumor (continued). "Consequently, using collected patient questionnaire data from the database of the Department of Pathology, Cancer Hospital, along with the corresponding KRAS and BRAF mutational status, we evaluated the associations between tumor molecular and epidemiological features." (PMID 26530529, 2015). "Thus, KRAS mutations apparently have a low or no selective advantage unless they are acquired early during carcinogenesis or the tumour is treated with EGFR-targeted agents." (PMID 25555261, 2015). "However, if expression of both mutant EGFR and mutant KRAS is detrimental, co-mutated cells are unlikely to survive during tumor evolution; therefore, they are unlikely to explain TKI resistance in an EGFR-mutant tumor." (PMID 26047463, 2015). "We report here that xenograft tumor growth of an oncogenic HRASG12V-transformed human cell line engineered to express activated PI3K is diminished upon knockdown of endogenous wild-type KRAS, and that this effect was rescued by re-expressing the wild-type, but not the C118S-mutant KRAS." (PMID 25902334, 2015). "Furthermore, although one tumor contained mutations in both KRAS and EGFR, the KRAS mutation, D33E, is not known to be activating." (PMID 26047463, 2015). "Side-by-side studies using comparable genetically engineered mouse models will be required to ascertain these effects, which could shed light on different selective constraints that KRAS- versus BRAF- mutant cells have for tumor initiation and progression in the intestinal epithelium." (PMID 26299805, 2015). "Therefore, other unknown functional molecules targeted by miR-193b, maybe together contribute to the tumor-inhibiting effect, which might arouse interesting further exploration in revealing the comprehensive network of miR-193b-KRAS axis in PDAC." (PMID 25905463, 2015). "In tumors where some cells have incurred activating mutations in KRAS, while others have not, miR-100 could accumulate in wild-type KRAS tumor cells through exosomal transfer, inhibiting mTOR and cell growth." (PMID 26132860, 2015). "KRAS/BRAF mutant allele ratio was consistently 1:1 (1.05, 1.06 and 1.00 by pyrosequencing) in 3 subareas re-isolated from cases P5, further supporting the presence of concomitant mutations in the same tumor cell population instead of different tumor subpopulations." (PMID 26498038, 2015). "The mutation rate of other oncogenes was not significantly different between the LGSCs and SBTs; however there was a trend towards a lower frequency of BRAF and KRAS mutants in the LGSCs and a higher rate of “wildtype” tumours, where no oncogenic mutation was identified." (PMID 26506417, 2015). "We speculate that this finding reflects specific aspects of mutated KRAS tumor biology rather than an irrelevance of KRAS in bev/chemotherapy outcome." (PMID 25888291, 2015). "For example, the KRAS oncogene participates in the signaling of the PI3K/PTEN/AKT and RAF/MEK/ERK pathways, consequently KRAS mutations constitute about 85% of all of the RAS mutations in human tumours, while NRAS mutations make up approximately 15%, and HRAS account for only 0.12 to 1%." (PMID 25932044, 2015). "Because the vast majority of signaling proteins, including those in the KRAS pathway, are ubiquitously expressed and activated to varying extents across different cell types, pure cancer epithelia were first isolated via LCM to minimize the confounding contribution of the tumor-associated stroma." (PMID 26468985, 2015). "The tumor positive for a KRAS G12D mutation also harbored a known activating GNAQ R183Q mutation, albeit at varying allelic frequencies (KRAS G12D at 6%, GNAQ R183Q at 30%), suggesting that the sample may be heterogeneous and that the KRAS mutant allele may be present in a sub-clone." (PMID 26440310, 2015). "Here, HROC60 cells acquired a KRAS mutation that was not detectable in the parental tumor." (PMID 26618628, 2015).
tumor (continued). "We hypothesized that the activation of the PI3K pathway in combination with Ras/MAPK pathway, via PTEN loss and overexpression of activated KRAS, respectively, is sufficient to promote tumor initiation and progression in a non-tumorigenic cell line." (PMID 26497685, 2015). "However, even with 4–6 mice, lung tumorigenesis was dramatically reduced as evidenced by significantly fewer tumor nodules and markedly smaller tumors in COX-2 null K-ras mice compared to that in K-ras mice, suggesting that the COX-2 pathway is important for KRAS mutation induced lung tumorigenesis." (PMID 26452035, 2015). "Moreover, treatment using cetuximab only for patients with tumors who expressed wild-type KRAS showed more favorable cost-effectiveness ratio than treating patients irrespective of tumor KRAS mutation status." (PMID 26075972, 2015). "Therefore, tumors with BRAF or KRAS mutations were in correlation with elevated serum level of tumor biomarkers of CRC and the association of tumor biomarkers and molecular status may indicate the poor prognosis of these patients." (PMID 26530529, 2015). "In addition, surrogate RNA onco-signatures of tissue biomarkers, also in 88% of localized KRAS mutant cancer patients as measured by the tumor-specific and pan-cancer SVM/LOOCV procedures, are readily available from a minute amount (100–500 pg) of platelet RNA." (PMID 26525104, 2015). "Considering that the in vitro inhibition of the BRAF downstream target MEK also affected MGL ligand expression, we assume that activating mutations in members of the MAPK pathway other than BRAF, such as KRAS and EGFR, may also cause aberrations in tumor cell glycosylation." (PMID 26172302, 2015). "In addition, the KRAS codon 12 mutated carcinomas in our study also displayed morphologic features typically associated with adverse behavior regardless of tumor location." (PMID 25929517, 2015). "Furthermore, when taking the percentage of neoplastic cells in individual samples and the allelic frequency of the variants into account, in contrast to most mutations in KRAS, EGFR and BRAF, a large proportion of the newly identified mutations appear to be present in only a subset of tumor cells." (PMID 25637035, 2015). "In this regard, we genetically demonstrate that the inability of KRASC118S to restore tumor growth of HRASG12V-transformed human cells upon knocking down endogenous KRAS could be restored, in large part, by introducing an activating mutation into the KRASC118S transgene." (PMID 25902334, 2015). "Concurrent somatic BRAF and KRAS mutations within the same tumor specimen have not been reported." (PMID 25013473, 2014). "No single tumor was identified that harbored KRAS and BRAF mutations." (PMID 24765171, 2014). "However, OS was prolonged in patients with KRAS wild-type vs. KRAS mutant tumor samples determined by DNA sequencing (18.3 vs. 15.9 months; p = 0.064), and was statistically significant when mutation status was determined by PNA-PCR (19.5 vs. 16.9 months; p = 0.025)." (PMID 25491325, 2014). "Considering the final endpoint, using Sanger sequencing we detected a KRAS mutation in 42.1% of adenocarcinomatous and pre-neoplastic lesions (in 40% of PDAC, 41.7% of IPMNs and in the 50% of inoperable neoplasms), while no KRAS mutations were observed in not adenocarcinomatous or in benign lesions." (PMID 24504548, 2014). "No mutations at KRAS:p.G12 or KRAS:p.Q61 were identified across the tumor cohort." (PMID 24529209, 2014).
tumor (continued). "One patient, who achieved a partial remission (PR) with IGF1R inhibitor treatment, but later developed resistance, demonstrated a KRAS mutation in the post-treatment resistant tumor, but not in the pre-treatment tumor suggesting that the RAF/RAS/MEK pathway was activated with progression." (PMID 25119929, 2014). "In KRAS-mutant lung ADCs, Sox9 overexpression may be secondary event associated with tumor progression, rather than directly downstream of the Kras pathway." (PMID 25004243, 2014). "Armed with the genetic evidence of mutations involving KRAS and CDK6/CDK14 as well as the response to single agent therapies, we reasoned that treatment with a combination of drugs addressing the key mutations associated with propagation and metastasis in the CB42 should result in tumor regression." (PMID 25162504, 2014). "There is evidence that not all KRAS mutations are equal and the different aminoacid substitutions could confer specific biological features to the tumor." (PMID 24952473, 2014). "Since the overexpression of Spry2 did not alter KRAS mutational frequencies, it was suggested that the tumor-suppressing activity of the overexpressed Spry2 might be applied at stages of carcinogenesis subsequent to KRAS mutation." (PMID 24744103, 2014). "A KRAS mutation was identified in the resistant tumor, but not in the pre-treatment tumor." (PMID 25119929, 2014). "A previous study reported that KRAS mutations in a tumor may not be detected in the bloodstream and suggested that this non-detection may be caused by the low DNA concentration, as well as the heterogeneity." (PMID 24884535, 2014). "In April 2009, the American Society of Clinical Oncology (ASCO) recommended that patients with metastatic CRC who are candidates for EGFR inhibitors have their tumor tested for KRAS mutations, and that those with a KRAS mutation in codon 12 or 13 not receive anti-EGFR treatment." (PMID 24788807, 2014). "From a practical perspective, small biopsies may not adequately represent a tumor's full mutational profile, particularly for later arising but prognostically important mutations such as those in the KRAS and BRAF genes." (PMID 24742923, 2014). "Regarding the identification of KRas mutations on snap-frozen adenocarcinomas, results were strictly identical to those previously obtained on FFPE samples (i.e., identification of G12S and G12D mutations in the KRas mutated tissues and wild-type status in the other two tumours)." (PMID 25184754, 2014). "The reasonable explanation for this is the heterogenity of cancer tissue, which means that the sections used in the detection only represented part of the tumor and did not contain the DNA carrying KRAS mutations that released into blood from other parts of tumor." (PMID 25491325, 2014). "Thus, one can speculate if the level of resistance to EGFR inhibitors would follow the expression levels of mutant KRAS transcripts in the different tumor compartments." (PMID 24280411, 2013). "Here we show that minor differences in the molecular nature of KRAS mutations stimulate distinct intracellular signalling pathways in normoxic conditions with different impact in basal levels of HIF-1α VEGF-A production and generation of a distinct vascular network in tumours." (PMID 23506169, 2013). "According to well-established criteria, a molecular analysis of exon 2 (codons 12 and 13) is routinely performed in formalin-fixed, paraffin-embedded (FFPE) tissue and the identification of a wild-type (WT) KRAS tumor may lead to a more tumor-specific and less toxic treatment for the patient." (PMID 23761841, 2013). "The rational selection of the first-line individualized therapy, between anti-EGFR therapy and anti-VEGF therapy, is only possible if the patient benefits of tumor KRAS mutation testing, whereas without this determination, the therapeutic choice would be done by default." (PMID 24133623, 2013).
tumor (continued). "If a tumor is positive for a KRAS mutation, no further molecular testing is required, and treatment recommendations will focus on chemotherapy because tumors harboring somatic mutations in KRAS, which encodes a GTPase downstream of EGFR, display greater resistance to these targeted drugs." (PMID 23341890, 2013). "The combined analysis can thus provide a rapid answer to whether the tumor harbors an activating KRAS mutation or not." (PMID 24280411, 2013). "Although KRAS mutation has been studied for the predictive value of tumor response to anti-EGFR treatment and also has been confirmed to be the highly predictive of resistance to anti-EGFR treatment, the prognostic value of KRAS mutation in synchronous and metachronous mCRC remains controversial." (PMID 24330663, 2013). "However, RBM5 and KRAS expression was not an independent factor associated with a higher rate of tumor recurrence." (PMID 23425895, 2013). "Moreover, KRAS-mutated tumours had a significantly improved survival in unadjusted, but not adjusted, analysis." (PMID 23800114, 2013). "In support of the mutator phenotype hypothesis, mutations in MLL3 seem to be acquired at a later stage of tumour development (passenger mutations) and are not initiators of tumour formation as opposed to driver mutations like KRAS G12V/D." (PMID 23152778, 2012). "As such, anti-EGFR drugs (Section 7.1.2) are not recommended in KRAS-mutated tumours." (PMID 22997602, 2012). "In the current series none of the good responders had a tumour with a KRAS codon 13 mutation." (PMID 22804917, 2012). "Therefore the use of these antibodies is restricted to patients with KRAS wild-type tumours." (PMID 22804917, 2012). "Five patients had a KRAS mutation in the primary tumour and not in the liver metastasis." (PMID 21364579, 2011). "Across tumor types, we demonstrated a higher prevalence of RAS (KRAS, NRAS) or BRAF mutations (47%) and KRAS mutations (38%) in patients with mutant PIK3CA compared to those with wtPIK3CA (mutant RAS or BRAF present in 24%, p = 0.001; mutant KRAS present in 16%, p = 0.001)." (PMID 21829508, 2011). "Thus, KRas+Akt-induced experimental gliomagenesis is closely associated with increased, predominantly vascular expression of SCF, providing a potential explanation for the increased MC numbers in the tumor tissues." (PMID 21949886, 2011). "Presence of KRAS mutation of cytology smears and lack of detection in corresponding resected tumor in one of our cases suggests that cytology smears may be more suitable and sensitive source for KRAS mutational analysis." (PMID 29147262, 2011). "All BRAF mutant tumours were non-responders and all mutually exclusive from mutated KRAS." (PMID 21439039, 2011). "The goal is to determine whether KRAS and EGFR mutation profile is stable during the metastatic progress and to investigate the clinical usefulness of mutational analyses in primary tumor versus in metastases for planning EGFR-targeted therapies for the treatment of patients with NSCLC." (PMID 21414214, 2011). "Tumor tissues from 504 patients with diverse cancers referred to the Clinical Center for Targeted Therapy at MD Anderson Cancer Center starting in October 2008 were analyzed for PIK3CA, RAS (KRAS, NRAS), and BRAF mutations using polymerase chain reaction-based DNA sequencing." (PMID 21829508, 2011). "None of these 9 tumours had a KRAS mutation either, which is in accord with others." (PMID 21901162, 2011). "Transcriptional profiles of AC and LCC tumours with and without KRAS mutation were compared." (PMID 21385341, 2011). "Lack of such comparison raises a possibility that in cases with lack of detection of KRAS mutation on cytology specimen may be secondary to tumor heterogeneity and may represent a false negative." (PMID 29147262, 2011).